TRIM5 (tripartite motif containing 5)
Description:
Capsid-specific restriction factor that prevents infection from non-host-adapted retroviruses. Blocks viral replication early in the life cycle, after viral entry but before reverse transcription. In addition to acting as a capsid-specific restriction factor, also acts as a pattern recognition receptor that activates innate immune signaling in response to the retroviral capsid lattice. Binding to the viral capsid triggers its E3 ubiquitin ligase activity, and in concert with the heterodimeric ubiquitin conjugating enzyme complex UBE2V1-UBE2N (also known as UBC13-UEV1A complex) generates 'Lys-63'-linked polyubiquitin chains, which in turn are catalysts in the autophosphorylation of the MAP3K7/TAK1 complex (includes TAK1, TAB2, and TAB3). Activation of the MAP3K7/TAK1 complex by autophosphorylation results in the induction and expression of NF-kappa-B and MAPK-responsive inflammatory genes, thereby leading to an innate immune response in the infected cell. Restricts infection by N-tropic murine leukemia virus (N-MLV), equine infectious anemia virus (EIAV), simian immunodeficiency virus of macaques (SIVmac), feline immunodeficiency virus (FIV), and bovine immunodeficiency virus (BIV). Plays a role in regulating autophagy through activation of autophagy regulator BECN1 by causing its dissociation from its inhibitors BCL2 and TAB2. Also plays a role in autophagy by acting as a selective autophagy receptor which recognizes and targets HIV-1 capsid protein p24 for autophagic destruction.
Synonyms: RNF88; TRIM5alpha
Tractability: PROTAC: UniProt records ubiquitination sites on it; ubiquitination databases record sites on it; its protein half-life has been measured.
Gene: Protein-coding gene on chromosome 11 (5,663,195 to 5,938,619, reverse strand). Ensembl gene ENSG00000132256.
Subcellular location: Cytoplasm; Nucleus
Subcellular location (Human Protein Atlas): Cytosol
Pathways (Reactome):
Immune System: Interferon gamma signaling
Gene Ontology:
Molecular function: identical protein binding; pattern recognition receptor activity; protein binding; protein homodimerization activity; protein kinase binding; protein-macromolecule adaptor activity; transcription coactivator activity; ubiquitin-protein transferase activity; ubiquitin protein ligase activity; zinc ion binding
Biological process: activation of innate immune response; antiviral innate immune response; autophagy; host-mediated suppression of symbiont invasion; positive regulation of canonical NF-kappaB signal transduction; positive regulation of MAPK cascade; protein K63-linked ubiquitination; regulation of lipopolysaccharide-mediated signaling pathway; regulation of protein localization; suppression of viral release by host; defense response to virus; innate immune response; regulation of gene expression; regulation of viral entry into host cell; positive regulation of DNA-templated transcription; protein ubiquitination
Cellular component: cytoplasm; cytoplasmic ribonucleoprotein granule; cytosol; omegasome; nucleus
Genetic constraint (gnomAD): Loss-of-function variants: 23 observed, 31.56 expected, observed/expected ratio (o/e) 0.73, 90% interval 0.52 to 1.03. The upper end of that interval is the gene's LOEUF score, 1.03, which puts it in group 4 of 6, group 1 being the genes least tolerant of losing a copy. Missense variants: 595 observed, 599.91 expected, observed/expected ratio (o/e) 0.99, 90% interval 0.93 to 1.06. Synonymous variants: 240 observed, 219.36 expected, observed/expected ratio (o/e) 1.09, 90% interval 0.98 to 1.22.
Homologues: Orthologues: chimpanzee TRIM5 (98% identical), macaque TRIM5 (87% identical), rabbit TRIM5 (57% identical), mouse Trim5 (51% identical), rat Trim5 (50% identical), mouse Trim12c (50% identical), mouse Trim30a (47% identical), mouse Trim30c (46% identical), mouse Trim30d (46% identical), rat Trim30c (45% identical), mouse Trim12a (32% identical), mouse Trim30b (20% identical). Paralogues in human: TRIM6 (56% identical), TRIM22 (53% identical), TRIM34 (53% identical), TRIM68 (34% identical), TRIM21 (32% identical), TRIM38 (32% identical), TRIM58 (28% identical), TRIM60 (28% identical), TRIM27 (27% identical), TRIM64 (26% identical), TRIM64B (26% identical), TRIM11 (26% identical), and 68 more.
Diseases named in the same sentence as TRIM5 in open-access papers:
TRIM5 is named in the same sentence as 34 diseases in open-access papers, as found by Europe PMC text mining. Sharing a sentence is not in itself a finding about the gene and the disease. The quoted sentences say what the papers report.
HIV-1 infection (37 papers, 2006 to 2025). The type species of lentivirus and the etiologic agent of acquired immunodeficiency syndrome (AIDS). "Lastly, TRIM5-knockout MDBK cells generated in this study displayed significantly higher susceptibility to HIV-1 infection." (PMID 36258028, 2022). "TRIM5α is a key cross-species barrier to retroviral infection, with certain TRIM5 alleles conferring increased risk of HIV-1 infection in humans." (PMID 33052966, 2020). "Other TRIM5 polymorphisms (rs10838525 and rs3740996) have been related to higher resistance to HIV-1 infection and TRIM5 rs3824949 GG is associated with higher levels of antibodies in response to measles and rubella vaccines." (PMID 27590274, 2016). "We studied TRIM5 variants that potently restrict HIV-1 infection (rhesus TRIM5α [RhT5] and New World owl monkey TRIM-cyclophilin A [TCyp]) and developed an in vitro model of RhT5 and TCyp expression in HIV-1-susceptible cell lines." (PMID 27440884, 2016). "It was argued that the human TRIM5 changed in response to PtERV exposure protecting humans but leaving them susceptible to a later HIV-1 infection." (PMID 23938750, 2013). "The macaque and owl monkey TRIM5 orthologues have been particularly well studied, due to the potent inhibition of HIV-1 infection in cells from these species, which is associated with strong interaction with the HIV-1 virion core." (PMID 24455433, 2013). "We found that B-LCLs expressing only TRIM5 alleles 1–5 efficiently restricted SIVsmE543 and HIV-1 infection, whereas B-LCLs expressing only TRIM5α molecule from the group of alleles 6–11 were more permissive for infection by these virus constructs." (PMID 20107597, 2010). "The susceptibility of M. leonina to HIV-1 infection is due to the dysfunctional TRIM5-CypA fusion in the TRIM5 locus." (PMID 19505341, 2009). "Here, we analyzed the susceptibility of the local species M. leonina in Yunnan to HIV-1 infection and the TRIM5 locus." (PMID 19505341, 2009). "The block to HIV-1 infection in lymphocytes from animals bearing the TRIM5-CypA allele was weaker than that in cells from wild type animals." (PMID 18389077, 2008). "TRIM5-knockout cells exhibited significantly greater susceptibility to HIV-1 infection." (PMID 36258028, 2022). "Interestingly, despite TRIM5’s relative inability to protect human cells from HIV-1 infection in vitro, human genetic studies have indicated that certain TRIM5 alleles confer increased risk of HIV-1 infection in people." (PMID 33052966, 2020). "In addition, we extended previous work on the in vitro susceptibility of purified donor CD4 T cells (n = 125) to HIV-1 infection, and on the susceptibility of HeLa cells that were stably transduced with the different TRIM5 variants." (PMID 16925802, 2006). "Similar to Nup153 and CPSF6, TRIM5 fusions to the FG-rich portion of POM121 inhibit HIV-1 infection." (PMID 37355754, 2023). "To investigate the impact of bovine TRIM5 on inhibition of HIV-1 infection in bovine cells, we depleted TRIM5 in MDBK cells via siRNA transfection." (PMID 36258028, 2022). "Consistent with the observation in MDBK cells, HIV-1 infection was significantly blocked in CRFK cells expressing bovine TRIM5 (blue)." (PMID 36258028, 2022). "In New World monkey cells, such as Owl monkeys (OWM, Aotus trivirgatus), a novel TRIM5-cyclophilin A fusion protein (TRIMcyp) exhibits a post-entry barrier to HIV-1 infection." (PMID 32477302, 2020). "In conclusion, these results show that HIV-1 infection is inhibited via the expected mechanism in the TRIM5-edited clone 6 cells." (PMID 33375604, 2020). "TRIM5 blocks HIV-1 infection in the cytoplasm, before reverse transcription is completed, by recognizing and binding the capsid protein lattice, thus interfering with the uncoating and ultimately with reverse transcription." (PMID 24455433, 2013).
HIV-1 infection (continued). "It is possible that these two processes mediated by TRIM5α are coupled; however, it appears that human TRIM5-mediated innate immune response to HIV-1 capsid cannot efficiently control HIV-1 infection in humans given the existing AIDS pandemic." (PMID 21866272, 2011). "Similar to their results, siRNA targeting TRIM5 increased permissiveness to HIV-1 infection up to 20 fold, which is roughly eight-fold more permissiveness than we observed in AGM cells transfected with the BTBD2 shRNA plasmid." (PMID 21092135, 2010). "Over the last decade, experiments seeking the causes of defined cellular blocks to HIV-1 infection uncovered three new RF genes, APOBEC3G (now considered to be the prototype of a cluster of ∼8 APOBEC3 genes), TRIM5, and Tetherin." (PMID 20808775, 2010). "The local species Northern pig-tailed macaque (M. leonina) was analyzed for the correlation of TRIM5 structure and HIV-1 infection." (PMID 19505341, 2009). "In contrast to the effect of the WT particle treatment, the effect of the dominant negative TRIM5 mutant on HIV-1 infection was evident when we used particles with SIVmac L4/5 and L6/7 (right, white vs. black diamonds, p = 0.007, paired t test)." (PMID 19650891, 2009). "TRIM5 confers a potent block to HIV-1 infection in Old World primates, while Cyclophilin A (CypA) enhances infection by direct interaction with the HIV capsid." (PMID 18673550, 2008). "Among primates, a particular case exists in owl monkey cells, which express a fusion protein between TRIM5 and cyclophilin A, TRIMCyp, specifically interfering with HIV-1 infection." (PMID 18613956, 2008). "TRIM5 plays an important role in protecting cells from cross-species transmission of retroviruses, so understanding the detailed mechanism by which CYPA regulates TRIM5’s restriction of HIV-1 will help inspire the development of new methods to inhibit HIV-1 infection." (PMID 39859212, 2025). "We demonstrated that bovine TRIM5 strongly inhibited HIV-1 infection." (PMID 36258028, 2022). "Consistent with previous studies, HIV-1 infection was mainly blocked by bovine TRIM5 in MDBK cells." (PMID 36258028, 2022). "TRIM5 is well known to restrict the HIV-1 infection at an early-stage of reverse transcription." (PMID 27590274, 2016). "Successful simian tropic (st) HIV-1 infection of pig-tailed macaques (M. nemestrina), which express a TRIM5-cyclophilin fusion (TRIM-Cyp) that is unable to restrict HIV-1, demonstrates that the HIV-1 host-range can include macaques when APOBEC3- and TRIM5-imposed restrictions are absent." (PMID 24086139, 2013). "While our STR studies were not intended to mimic a clinically relevant setting, our results may provide an answer as to how human TRIM5, which has historically been considered ineffective as an HIV-1 restriction factor, can confer protection against HIV-1 infection risk in people." (PMID 33052966, 2020). "Finally, associations of polymorphisms in the TRIM5 gene with variations in rubella virus-specific immune responses (TNF-α, GM-CSF and IL-2) have been observed, in concordance with recent findings on the role of the same TRIM5-gene SNPs in the immune response to retroviral (HIV-1) infection." (PMID 21933421, 2011). "Interestingly, a previous study by the Luban laboratory uncovered a unique retrotransposition event in owl monkey, the only New World primate that is resistant to HIV-1, resulting in the expression of a TRIM5-Cyclophilin A (TRIMCyp) fusion protein that is potent in blocking HIV-1 infection." (PMID 21866272, 2011). "Interestingly, CypA and Trim5 were also found to resistant to HIV-1 infection." (PMID 21192783, 2010). "We have previously reported that the TRIM5-Cyclophilin A (TRIMCyp) fusion in pig-tailed macaques (Macaca nemestrina) is dysfunctional in restricting HIV-1, which may explain why pig-tailed macaques are susceptible to HIV-1 infection." (PMID 19505341, 2009).
HIV-1 infection (continued). "Given that HIV-1 benefits from activation of TAK1 by Vpr at the early stage of HIV-1 infection, it is possible that TAK1 is activated via different mechanisms by Vpr or TRIM5/tetherin." (PMID 24912525, 2014). "To investigate whether V86M and H87Q CA mutants could evade inhibition by bovine TRIM5, we used owl monkey kidney (OMK) cells, RM-derived FRhK-4 cells, and MDBK cells for infection experiments because HIV-1 infection was blocked in these cell lines." (PMID 36258028, 2022). "HIV-1 infection of cell lines can be inhibited by the expression of an artificial antiviral protein, comprising the RBCC domains of owl monkey tripartite motif-containing protein 5 (TRIM5) fused to human CypA (TRIM-CypA)." (PMID 26679998, 2016). "We conclude that although NUP153C in the context of the Trim5 protein likely engages HIV-1 CA earlier than endogenous NUP153 protein, the novel fusion nonetheless affords the analysis of the NUP153-CA interaction in the context of HIV-1 infection." (PMID 24130490, 2013). "We used a CHO-derived cell line (pgsA), because it can be very efficiently infected by VSV-G pseudotyped retroviruses and does not express a TRIM5 protein that restricts MLV or HIV-1 infection." (PMID 23505372, 2013). "The effect of priming correlated with the species-specific ability of TRIM5 to restrict the priming virus, as priming with an equal CrFK MOI of a WT capsid-bearing virus that was otherwise identical to HIV-1 CA P90A was significantly less efficient in restricting WT HIV-1 infection of THP1 cells." (PMID 33052966, 2020). "Although human TRIM5 is not thought to strongly restrict HIV-1 infection in humans, we hypothesized that in certain cases, for example, under selective pressure to escape Gag-directed CD8+ T-cell responses, HIV-1 variants sensitive to human TRIM5 may arise." (PMID 27440884, 2016). "In vitro analyses demonstrated that cells expressing PM TRIMCyp restricted HIV-2 but not HIV-1 infection, suggesting that the characteristic isoform of the TRIM5 gene in PMs may be one of the reasons for their greater susceptibility to HIV-1 infection." (PMID 22113010, 2012). "While some host factors are hijacked by the HIV-1 capsid to prevent the innate sensing of HIV-1 infection (e.g., cyclophilin A (CypA) and specificity factor subunit 6 (CPSF6)), others, such as tripartite motif-containing protein 5 (TRIM5) and NONO, activate innate immune signaling." (PMID 36899868, 2023). "Moreover, novel isoforms of TRIM5 [TRIM5θ, which lacks B30.2 (SPRY) domain and TRIM5η, which has a deletion of the entire exon 7] expressed by PTMs do not restrict HIV-1 infection." (PMID 32477302, 2020).
viral infection (21 papers, 2008 to 2025). "The STRING database revealed that three possible target proteins interacted with SLFN, including BST2, SAMHD1, and TRIM5, previously implicated in viral infection." (PMID 36090985, 2022). "Similarly, studies establishing direct interactions between Nups and CA either by demonstrating susceptibility to chimeric TRIM5-fusion proteins or by in vitro biochemical approaches may or may not indicate that such interactions have functional consequences in the context of virus infection." (PMID 39853118, 2025). "Viral infection experiments in TRIM5-overexpressing cells revealed that TRIM5 overexpression significantly increased the expression of IFN-α and IFN-β from 6 to 24 hpi (P < 0.01)." (PMID 39143491, 2024). "One possible reason for this is that the diversification of TRIM5 was sufficient to counteract the variety of viral diseases in most mammals, and, therefore, the same process happening in TRIM22 would be evolutionarily redundant." (PMID 35215944, 2022). "Single nucleotide polymorphisms (SNPs) at TRIM5 and TRIM22 genes have shown to influence several viral infections such as human immunodeficiency virus (HIV), hepatitis B, as well as measles and rubella vaccination." (PMID 27590274, 2016). "Ancient epidemics of viral infection likely contributed to the selection of modern genes with potent antiretroviral activity, such as the TRIM5 and APOBEC3 families of antiretroviral factors." (PMID 18927623, 2008). "Among these, several are known or suspected to be involved in defending the cell against viral infection, including TRIM5, TRIM19, TRIM25 and TRIM28." (PMID 18389077, 2008). "Viral infection experiments were conducted on 3D4/21 cells with overexpression or inhibited expression of TRIM5 to determine whether TRIM5 regulates the expression of cytokines related to the RIG-I-like receptor signalling pathway during SVA infection." (PMID 39143491, 2024). "Thus, we propose that despite the lack of an overt, positively-selected site of viral interface on TRIM34, TRIM34 restricts viral infection through interaction with the rapidly-evolving TRIM5 protein." (PMID 37608289, 2023). "TRIM5-p25 heterodimers docked to the pre-integration complex likely suffer degradation by the proteasome thanks to TRIM5 polyubiquitination, thus diminishing the integration of retrotranscribed viral DNA into the host cell genome and, therefore, viral infection." (PMID 23917352, 2013). "In vivo studies will be required to determine how TRIM5 is regulated, whether regulation changes in response to viral infection, and to identify the patterns of TRIM5 expression in cell types responsible for initial infection and spread in vivo." (PMID 20808775, 2010). "The infection of a recombinant SeV expressing TRIM5 without the SPRY domain caused marked enhancement of HIV-1-L4/5S-GFP virus infection without prior particle treatment (crosses vs. asterisks)." (PMID 19650891, 2009). "The PTM genome encodes a TRIM5–cyclophillin A fusion protein that changes the specificity of viral species recognition by TRIM5α and is thought to render PTM more susceptible to certain viral infections including some simian immunodeficiency viruses and flaviviruses." (PMID 40961197, 2025). "TRIM5, a member of the TRIM protein family, is involved in innate immunity and acts as a barrier against specific viral infections." (PMID 39611400, 2024). "In the case of viral infections, PRRs, such as RIG-I and TLRs, and autophagy receptors tripartite motif containing 5 (TRIM5) and p62, can detect viral components and thereby induce selective autophagy against the sensed virus." (PMID 30406039, 2018). "Viral infection experiments showed that the mRNA expression of the SVA VP3 gene did not significantly differ between the pEGFP-N1 + shRIG-I and pEGFP-N1-TRIM5 + shRIG-I groups, indicating that TRIM5 regulates the RIG-I signalling pathway." (PMID 39143491, 2024).
viral infection (continued). "This increase in GFP signal occurs because TRIM5 becomes saturated by the RFP virus and can no longer efficiently block GFP virus infection." (PMID 33524070, 2021).